ETS1 (ETS proto-oncogene 1, transcription factor)
Diseases named in the same sentence as ETS1 in open-access papers (continued):
Sharing a sentence is not in itself a finding about the gene and the disease.
Obesity (8 papers, 2018 to 2024). Accumulation of substantial excess body fat. "While none of the targets were experimentally verified in all four diseases, we found that PTEN was targeted in atherosclerosis, NAFLD and T2DM/IR, while ETS1 was targeted in atherosclerosis, obesity and T2DM/IR." (PMID 30369883, 2018). "As in the adipose tissue of patients with obesity, an inverse correlation between ETS1 and miR-221 expression levels has been reported in many malignancies, thus indicating that miR-221 may induce oncogenesis via ETS1." (PMID 34681797, 2021). "Similarly, miR-126 had altered expression in obesity and may modulate CCL2 (chemokine ligand 2) through genes that encode ETS1, MAX, NFKB1, RELB, and STAT6 proteins." (PMID 36355127, 2022). "Taken together, these findings indicated that in the presence of sex, obesity, and T2D, the expression levels of DVL2, ETS1, and IL1RAP are dependent on the type of AT depot." (PMID 38139277, 2023). "Comparison of differential transcriptomic profiles and GWAS/WGS profiles identified 3 significant shared genes (ETS1, RGS6, BRINP2) commonly present between obesity and schizophrenia pair in both analyses." (PMID 37494308, 2023). "This enabled us to pinpoint 3 significant common target genes (ETS1, DVL2, and IL1RAP) exhibiting markedly distinct expression profiles in both VAT and SAT among patients with obesity and T2D." (PMID 38139277, 2023). "Collectively, our data suggest that the miR-221-3p/222-3p cluster could potentially regulate AT functionality through the modulation of DVL2, ETS1, and IL1RAP during obesity and T2D." (PMID 38139277, 2023). "Additionally, the binding site prediction analysis further supported the direct regulation of miR-221-3p and miR-222-3p in the gene regulatory networks of ETS1, DVL2, and IL1RAP concerning obesity and T2D." (PMID 38139277, 2023).
oral squamous cell carcinoma (8 papers, 2014 to 2024). "Ets-1 has been implicated in human oral squamous cell carcinoma (OSCC), and ets-1 levels appear to correlate well with the grade of invasiveness and metastasis." (PMID 24864247, 2014). "In gastric tumors and oral squamous cell carcinomas, the deregulation of ETS-1 was related with the invasive behavior and cancer metastasis." (PMID 27036016, 2016). "Cooperative upregulation of ICAM1 gene transcription by ETS-1 and autoimmune regulator (AIRE) in human oral squamous cell carcinoma cells, and by ETS-1 and signal transducer and activator of transcription 1 (STAT 1) in human HEK293 and monkey COS-1 kidney cell lines are also reported." (PMID 38984117, 2024). "In the Cancer Genome Atlas (TCGA) dataset of four oral squamous cell carcinoma tissues, EHF mRNA levels were not correlated negatively with those of ETS1, while a weak negative correlation was detected only in the GSE37991 dataset." (PMID 33712555, 2021).
osteosarcoma (8 papers, 2012 to 2025). A usually aggressive malignant bone-forming mesenchymal neoplasm, predominantly affecting adolescents and young adults. "Based on the present findings, we propose a mechanism by which daraxonrasib suppresses the proliferation and metastatic ability of KRAS mutant osteosarcoma cells by inhibiting overactive AKT/ETS1 signaling." (PMID 40779492, 2025). "The involvement of Ets-1 in the transcriptional activity of TXNIP has previously been reported in studies that observed induction of TXNIP by synthetic retinoids in osteosarcoma cells and in the regulation of TXNIP expression in pancreatic cells." (PMID 35888758, 2022). "A previous report suggested that Ets-1 activates the human MDR1 promoter in the human osteosarcoma cell line Saos-2." (PMID 32131547, 2020). "As Ets-1 is a well-defined pro-metastatic factor in osteosarcoma, we supposed that the pro-metastatic effect of PVT1 in BMSC-EXO was exerted via specifically raising ERG expression." (PMID 31699956, 2019). "Out of the differentially modulated genes, those implicated in stem cell and osteosarcoma biology, such as PPARG, ETS1, WNT1, WNT5B, SOX2, NANOG, POU5F1, nestin, and ALDH were chosen for further analysis." (PMID 22870217, 2012). "We then performed co-immunoprecipitation experiments using an anti-Ets-1 antibody-agarose conjugate in MDA-MD-231 cells and in an osteosarcoma cell line, MG63, which also expresses Ets-1." (PMID 23405229, 2013). "In osteosarcoma, KRAS inhibition decreased MMP1, MMP9, and AKT/ETS1 signaling." (PMID 40779492, 2025). "The co-culturing of BMSC-EXO and ERG-interfering MNNG/HOS cells (MNNG/HOSsi-ERG) reduced the malignancy of osteosarcoma cells, while the co-culturing of BMSC-EXO and Ets-1-interfering MNNG/HOS cells (MNNG/HOSsi-Ets-1) did not negate such response." (PMID 31699956, 2019).
renal carcinoma (8 papers, 2018 to 2024). A carcinoma arising from the epithelium of the renal parenchyma or the renal pelvis. "The results of cell experiments were performed to compare the mRNA levels of ELK3 and ETS1 between human renal cortical proximal tubular epithelial cell line HK-2 and human renal carcinoma cell line A498." (PMID 38287102, 2024). "ELK3 and ETS1 mRNA levels were compared between human renal cortical proximal tubular epithelial cell line HK-2 and human renal carcinoma cell line A489." (PMID 38287102, 2024). "We also showed that overexpression of CBX7 decreased ETS1 expression in renal cancer cells." (PMID 35342353, 2022). "ETS1 was the most changed candidate after CBX7 silencing, and this phenomenon was observed in renal cancer cells." (PMID 35342353, 2022).
atherosclerosis (7 papers, 2013 to 2024). A disease characterized by the build-up of fatty material and calcium deposition in the arterial wall resulting in partial or complete occlusion of the arterial lumen. "The predicted dysregulation of downstream targets following the inhibition of SIRT1 and ETS1 was also associated with increased inflammation and atherosclerosis, as validated by animal models studies." (PMID 39125657, 2024). "The direct inhibition of CDH5 following ETS1 inhibition led to the predicted activation of SHC1-induced atherosclerosis in this model." (PMID 39125657, 2024). "A possible mechanism of ETS1 in attenuating atherosclerosis has also been described via the mediation of 17b-oestradiol." (PMID 39125657, 2024). "In mice BDNF decreases VE-cadherin cleavage to reduce atherosclerosis and promotes vascular integrity through Ets1-mediated VE-cadherin expression." (PMID 31659205, 2019). "Hypoxia-induced HIF-1a/VEGF/Ets-1 cascade was suggested as important for angiogenesis in human atherosclerosis." (PMID 26006236, 2015). "Here we focused on five genes (Tgfbr1, Zeb1, Hdac2, Rab5a, and Ets1), which were all identified by miFDR alone, and discussed their potential roles in the context of diesel particle exposure and atherosclerosis." (PMID 24564975, 2013). "It is speculated that the role of Ets-1 in atherosclerosis may have the same activities." (PMID 26006236, 2015). "• Ets1 (up-regulated in DE-rats with 1.69 folds) may be related to atherosclerosis in two ways." (PMID 24564975, 2013). "The mechanosensor Piezo1 and the downstream transcription factors c‐JUN and ETS1 regulate KDM5B expression, and KDM5B potentially contributed to atherosclerosis by regulating endothelial inflammation." (PMID 39643939, 2024).
Hyperglycemia (7 papers, 2014 to 2024). An increased concentration of glucose in the blood. "In conclusion, ets1 contributes to hyperglycemia-mediated endothelial inflammation via upregulation of PTP1B expression." (PMID 35607953, 2022). "In the present study, hyperglycemia/high glucose was found to increase ets1 protein and mRNA levelsin vivo andin vitro." (PMID 35607953, 2022). "Previous studies showed that protein tyrosine phosphatase 1B (PTP1B) and ETS proto-oncogene 1 (ets1) are involved in hyperglycemia-induced endothelial inflammation." (PMID 35607953, 2022). "Additionally, the downregulation of IGF1 via the ETS1/MMP1 pathway in this prediction model contributed to hyperglycemia, which has been validated by studies on the b-cells of diabetic transgenic mice." (PMID 39125657, 2024). "However, the exact mechanism by which ets1 regulates endothelial adhesion molecule expression in hyperglycemia condition is still not well known." (PMID 35607953, 2022). "HMGB1 mediates hyperglycemia-induced cardiomyocyte apoptosis via ERK/Ets-1 signaling pathway." (PMID 26623724, 2016). "In conclusion, inhibition of HMGB1 may protect against hyperglycaemia-induced cardiomyocyte apoptosis by down-regulating ERK-dependent activation of Ets-1." (PMID 25210949, 2014). "Ets1, a member of the ETS family of transcription factors, has been reported to participate in hyperglycemia-induced endothelial-to-mesenchymal transition (EMT), thus mediating endothelial injury." (PMID 35607953, 2022). "Ets1, as a member of the ETS family of transcription factors, is involved in hyperglycemia-mediated endothelial-to-mesenchymal transition, thus mediating endothelial injury." (PMID 35607953, 2022). "The present study indicated that ets1 cooperated with KMT5A to transcribe PFN2, thus contributing to hyperglycemia-induced EndMT in the glomerular endothelial cells of DN patients and rats." (PMID 34238215, 2021). "In this study, we hypothesized that ets1 modulates PTP1B expression, thus playing a crucial role in hyperglycemia-induced vascular endothelial inflammation." (PMID 35607953, 2022). "With hyperglycaemia, increased HMGB1 level could promote cardiac cell death via the nuclear transcription factor Ets-1." (PMID 25210949, 2014).
lung adenocarcinoma (7 papers, 2015 to 2025). A carcinoma that arises from the lung and is characterized by the presence of malignant glandular epithelial cells. "Upon searching published papers and the LncMap database, we identified that five TFs—DDX17, STAT1, PPARG, ETS1, and E2F6—were closely associated with adenocarcinoma of the lung and HCG23." (PMID 32322582, 2020). "We also show that Zeb1 and Ets1 are expressed together at the invasive edge of K-Ras-initiated mouse lung adenocarcinomas, and there is a significant correlation between expression of Ets1 and Zeb1 in human lung adenocarcinoma." (PMID 25880398, 2015). "To check if Ets1 also follows Zeb1 expression in human lung adenocarcinomas, we examined microarrays of 59 human lung adenocarcinomas and compared expression of Ets1 and Zeb1 mRNAs." (PMID 25880398, 2015). "Although the correlation between Ets1 and Zeb1 in lung adenocarcinoma seen above is consistent with an amplification loop between Ets1 and Zeb1, these results are also consistent simply with the previously documented induction of Zeb1 by Ets1." (PMID 25880398, 2015). "Consistent with such an amplification loop, we correlate expression of Ets1 and Zeb1 in mouse and human lung adenocarcinoma." (PMID 25880398, 2015). "In lung adenocarcinoma, ETS1 was validated as a downstream target of miR-204-3p." (PMID 39941022, 2025). "Furthermore, it was previously shown that the expression of miR-203a-3p and miR-204-3p is downregulated in PTC compared to NMT, and ETS1 was shown to be a downstream target of miR-204-3p in lung adenocarcinoma." (PMID 39941022, 2025). "We examine expression of Ets1 and Zeb1 in K-Ras initiated mouse lung adenocarcinomas." (PMID 25880398, 2015). "Similarly, a recent report also demonstrated that miR-365 could repress EMT in lung adenocarcinoma through targeting ETS1." (PMID 33292210, 2020).
non-small cell lung carcinoma (7 papers, 2011 to 2025). A group of at least three distinct histological types of lung cancer, including non-small cell squamous cell carcinoma, adenocarcinoma, and large cell carcinoma. "A previous study has revealed that the transcription factor E26 transformation-specific-1 (ETS1) could affect disease progression in patients with non-small-cell lung cancer by up-regulating expression of miR-29b in the immune-evasion disease subtype." (PMID 33407520, 2021). "In non-small cell lung cancer, miR-512-5p expression is down-modulated and miR-512-5p overexpression impedes cancer cell multiplication, migration, and invasion, and induces apoptosis by targeting ETS1." (PMID 34765599, 2021). "Considering that in non-small cell lung cancer and hepatocarcinoma cells c-JUN has been involved in miR-221/-222 activation, it is also important to point out the capability of ETS-1 to associate and cooperatively bind with the AP-1 transcription complex to regulate gene expression." (PMID 21711453, 2011). "ETS1, another ETS member, affects disease in patients with non-small-cell lung cancer via up-regulation of miR-29b expression in the immune-evasion subtype." (PMID 33407520, 2021).
psoriasis (7 papers, 2017 to 2026). An autoimmune condition characterized by red, well-delineated plaques with silvery scales that are usually on the extensor surfaces and scalp. "Other genetic variants associated with psoriasis and related to IL-23 correspond to SOCS1 (coding for a suppressor of cytokine signal involved in Th17 differentiation) and ETS1 (coding ETS protooncogene 1 protein, involved in the negative regulation of Th17 differentiation)." (PMID 37628670, 2023). "ETS-1/rs6190776 5 promotes IFN-γ secretion and Th1/Th17 cell differentiation, potentially driving psoriasis." (PMID 39883516, 2024). "ETS-1, STAT3, and IFN-γ are important regulators involved in the differentiation of Th1 and Th17 cells, and their relationship with psoriasis and miR-125a-5p remains to be elucidated." (PMID 37773129, 2023). "miR-125a-5p may have therapeutic potential in psoriasis by restoring the suppressive function of Tregs on Th17 cells through targeting STAT3, and on Th1 cells indirectly through targeting ETS-1 and IFN-γ." (PMID 37773129, 2023). "In conclusion, the present study provides evidence that miR-125a-5p may have a therapeutic potential in psoriasis by restoring the suppressive function of Tregs on Th17 cells through targeting STAT3, and on Th1 cells indirectly through targeting ETS-1 and IFN-γ." (PMID 37773129, 2023).
head and neck squamous cell carcinoma (6 papers, 2019 to 2024). A squamous cell carcinoma that arises from any of the following anatomic sites: lip and oral cavity, nasal cavity, paranasal sinuses, pharynx, larynx, and salivary glands. "Therefore, dasatinib, an inhibitor of Src kinase activity, can effectively reduce Ets1 protein and significantly suppress the development of metastatic and invasive cisplatin-resistant head and neck squamous cell carcinoma." (PMID 36305724, 2022). "Recently, a study showed that inhibition of the Src/Ets1 pathway, which results in downregulation of Ets1 protein level, may provide treatment for cisplatin-resistant head and neck squamous cell carcinoma." (PMID 36305724, 2022). "ETS1 is required for ZEB2-induced EMT phenotype, where it regulates ZEB2-mediated expression of Twist and MMP-9, and can function as a master regulator of TGF-β-associated EMT in the mesenchymal subtypes of head and neck squamous cell carcinoma (HNSCC)." (PMID 32824207, 2020). "We investigated the role of the ETS-1 transcription factor in Head and Neck Squamous Cell Carcinoma (HNSCC) in multiple cisplatin-resistant HNSCC cell lines." (PMID 31118072, 2019). "Here we focus on Head and Neck Squamous Cell Carcinoma (HNSCC) and discover that higher expression of ETS1 is specifically more pronounced in the mesenchymal subtypes of HNSCC, which represent tumors with enriched expression of Epithelial to Mesenchymal Transition (EMT) markers and inflammation." (PMID 31306413, 2019).
invasive breast carcinoma (6 papers, 2004 to 2025). A carcinoma that infiltrates the breast parenchyma. "Previous work has implicated Ets1/Ets2 and c-Myc collaboration in invasive breast cancer and in thyroid cancer in humans." (PMID 24968297, 2014). "In particular, quantification of the expression of EPO, ETS1, PGK1, TPI, LDHA and ENO1 in a primary tumor sample provides information on the risk of recurrence for patients with early-stage invasive breast cancer." (PMID 28430808, 2017). "Elevated expression of both Ets1 and Ets2 has been identified in invasive breast cancers and correlated with increased expression of p160 nuclear receptor coactivators." (PMID 23874775, 2013). "Previously, using in situ hybridisation, mRNA for Ets-1 was reported to be increased in invasive breast cancers vis-à-vis in in situ lesions." (PMID 15365563, 2004). "In addition, elevated expression of Ets1 and Ets2 identified in invasive breast cancers has been correlated with increased expression of the p160 nuclear receptor coactivators NCOA1 (SRC1) and NCOA3 (AIB/SRC3)." (PMID 23874775, 2013). "Notably, previous studies have reported increased ETS1 mRNA levels in invasive breast cancer." (PMID 41462902, 2025).
metastatic melanoma (6 papers, 2011 to 2024). A melanoma that has spread from its primary site to another anatomic site. "Here we report that Ets-1 destruction is regulated by the deubiquitinating enzyme, Usp9x, and has major impact on the tumorigenic program of metastatic melanoma." (PMID 28198367, 2017). "Altogether, these results suggest that Usp9x overexpression is an early event in expansion of primary and metastatic melanoma, involving stabilization of Ets-1 to amplify NRAS expression." (PMID 28198367, 2017). "It was found that a phosphorylated part of the ETS1 protein induced miR-222 transcription in metastatic melanoma." (PMID 26627005, 2015). "In particular, primary and metastatic melanomas expressed high and low amounts of ETS-1 at mRNA and protein levels, respectively." (PMID 21711453, 2011). "The Me665/2 metastatic melanoma, displaying a very low level of endogenous ETS-1, was transduced with the Tween-lentiviral vector overexpressing ETS-1." (PMID 21711453, 2011). "CYT-high metastatic melanomas had recurrent copy number amplifications in loci 1p12 (NOTCH2), 1q44 (OR2M4), 7q36.1 (KCNH2), 11q13.3 (FGF3/4), 12p11.23 (MED21) and 12q13.3 (R3HDM2) and deletions in 1p22.1 (RHOC, NRAS), 9p21.3 (CDKN2B), 10q23.2 (miR346), 11q23.3 (ATM, CHEK1, ETS1) and 15q15.3 (CASC4)." (PMID 33779796, 2021). "In metastatic melanoma, the P-T38-activated fraction of c-ETS-1, by competing with c-ETS-1 for binding to DNA, may increase AP-1-driven transcription of those targets, such as miR-222, containing ETS-1 and AP-1 binding sites in close proximity on their promoters." (PMID 21711453, 2011).
renal cell carcinoma (6 papers, 2013 to 2025). "Statistical analyses demonstrated that ETS1 expression was effectively associated with tumour size (p = 0.018), T stage (p = 0.003), and Fuhrman grade of patients with renal cell carcinoma (p = 0.011)." (PMID 30082686, 2018). "In renal cell carcinoma (RCC), curcumin downregulates the expression of ETS-1 in a dose- and time-dependent manner." (PMID 41019994, 2025).
squamous cell carcinoma (6 papers, 2007 to 2023). A carcinoma arising from squamous epithelial cells. "Ets-1 has been shown to highly express within the malignant keratinocytes and correlate with the invasive and metastatic potential of the tumor and linked to the pathogenesis of squamous cell carcinoma." (PMID 28672814, 2017). "As a downstream effector of the Ras/MAPK pathway, the transcription factor ETS1 is only expressed in the proliferative layer of stratified skin epithelium tissue, and it is also expressed robustly in squamous cell carcinomas." (PMID 36652264, 2023). "Squamous cell carcinomas might regulate cathepsin B expression through transcription factors Ets1, Sp1, and Sp335, ultimately leading to immune resistance and tumor progression." (PMID 37805623, 2023). "Interestingly, the Ets1 oncogene is over-expressed in many human squamous cell cancers and over-expression is highly correlated with invasion and metastasis." (PMID 19142229, 2009). "It has been shown that expression of E-cadherin is increased in stably ETS-1-overexpressing cells, indicating that ETS-1 by itself has no activity to induce EMT in human squamous carcinoma cells." (PMID 25421630, 2015).